MC4R (melanocortin 4 receptor)
Diseases named in the same sentence as MC4R in open-access papers (continued):
Sharing a sentence is not in itself a finding about the gene and the disease.
Obesity (continued). "By using in silico prediction tools as a starting point, two MC4R variants that are most likely to be associated with an obesity phenotype are I170V and R165Q." (PMID 26788538, 2016). "In other words, losing the function of both MRAP2 and MC4R causes a milder obesity than losing the function of MC4R alone, suggesting that MRAP2 can promote weight gain through a mechanism that is distinct and independent from the regulation of the MC4R." (PMID 26829592, 2016). "This mouse model shows that obesity caused by Mc4r deficiency can promote atherosclerosis already under cholesterol-free chow." (PMID 28030540, 2016). "A single gene mutation can be linked to obesity in 5–7% of obese children, and the most common monogenetic cause of childhood obesity is a mutation in the melanocortin-4 receptor (MC4R) gene." (PMID 27738543, 2016). "We found new evidence that the MC4R rs17782313 C allele interacts with mental stress to promote obesity; but in this population, only in subjects with high stress." (PMID 27213003, 2016). "MC4R is one of the most common genetic causes of obesity and this gene participates in appetite regulation and energy balance." (PMID 27788139, 2016). "First, we did not assess other candidate genes which have been associated with obesity such as melanocortin-4 receptor (MC4R) gene as well as BDNF." (PMID 27196523, 2016). "There was a positive interaction between MC4R variants and mental stress levels that was significantly associated with the risk of obesity after adjusting for age, gender, residence area, daily energy intake, smoking status and physical activity." (PMID 27213003, 2016). "The importance of our case is that it shows the obesity phenotype seen in MC4R mutation carriers in a patient heterozygous for a full MC4R gene deletion." (PMID 27738543, 2016). "In humans, disabling mutations of MC4R are the most common cause of monogenic obesity and found in up to 6% of severely obese patients." (PMID 26113808, 2015). "In particular, EA female smokers who carry the MC4R obesity susceptibility allele had a %MBMI that was 5.48 % higher than nonsmokers that carry the allele (p = 8.4E–06)." (PMID 26537541, 2015). "In accordance with this aspect, it has been shown that the disruption of the POMC and melanocortin receptor 4 (MC4R) genes in mice models causes obesity, while MC3R gene-deficient mice have normal food consumption but accumulate fat." (PMID 25999818, 2015). "Mutations in the melanocortin 4 receptor (MC4R) gene are the most common genetic cause of human obesity." (PMID 26011903, 2015). "In conclusion, most common genetic variants for BMI identified through GWAS in Europeans have small and directionally consistent effects on obesity risk in this Pakistani population, with the MC4R and TEMEM18 loci conveying the largest effects." (PMID 26683835, 2015). "For example, candidate gene studies of MC4R common genetic variants revealed that the gain-of-function mutation of the variants lower the risk of obesity." (PMID 25825681, 2015). "Our finding with MC4R (rs17782313) T>C and its association with physical activity is consistent with a prior report that this is an important obesity susceptibility genetic locus that also associates with physical activity." (PMID 26495240, 2015). "MC4R mutations represent the most common form of human monogenic obesity, impacting 0.2–5.6% of individuals with severe early onset obesity." (PMID 25825681, 2015). "The common variants FTO rs9939609 and MC4R rs17782313 were genotyped and their relationship with obesity-related traits was evaluated." (PMID 26032905, 2015). "Common variants near the MC4R locus are associated with adiposity, body weight, risk of obesity and insulin resistance at a population level." (PMID 26113808, 2015). "Previous studies have shown that mutations causing MC4R inactivation lead to severe and monogenic forms of obesity." (PMID 26363598, 2015).
Obesity (continued). "Low frequency variants in MC4R were identified in morbid obese individuals (BMI > 40 kg/m2) and were associated with obesity." (PMID 26363598, 2015). "Variants in MC4R are associated with monogenic obesity and show differential effects on BMI by sex and age, with a greater influence on adolescent females." (PMID 26537541, 2015). "While the role of MC4R in monogenic obesity is well-defined, the role of MC3R mutations in human monogenic obesity is debated (Zegers, Beckers & Hendrickx, 2013)." (PMID 25825681, 2015). "Monogenic mutations such as those described for LEP, LEPR, POMC, and MC4R cause only a minority of obesity cases whereas in most individuals obesity is based on a polygenic predisposition amplified by an obesogenic Western lifestyle." (PMID 26470795, 2015). "Inactivating mutations of the melanocortin-4 receptor (MC4R) cause early-onset severe obesity in humans." (PMID 25136332, 2014). "Mutations in the melanocortin-4 receptor (MC4R) represent the commonest genetic form of obesity and are associated with hyperphagia." (PMID 25062455, 2014). "Together these data point to the complex involvement of MC4R in obesity, metabolism and weight-loss." (PMID 24705671, 2014). "Inactivating mutations of the MC4R cause early-onset severe obesity, which is the most common monogenic form of obesity in humans." (PMID 25136332, 2014). "In conclusion, in this population-based study, both rare and common variants in/near MC4R influence obesity in American Indian children and adults." (PMID 25103139, 2014). "MC4R, one of the most important genes associated with weight gain and increased risk for obesity, has been shown to play a role in the modulation of food intake and energy homeostasis." (PMID 24885933, 2014). "Since obesity is very common among American Indians, the high prevalence of this disease cannot be solely explained by these rare MC4R mutations." (PMID 25103139, 2014). "The anorexigenic properties of α-MSH signaling are also demonstrated by hyperphagia-induced obesity that develops following targeted destruction of MC4R, as well as the association between late-onset obesity and polymorphisms of the MC4R in human populations." (PMID 26237477, 2014). "Genetic variants within the MC4R coding region have been found to be associated with severe and common forms of obesity." (PMID 24820477, 2014). "Genome-wide association studies (GWASs) in Caucasians and other ethnic groups have identified common non-coding variants near MC4R that are reproducibly associated with fat mass, body weight and risk of obesity." (PMID 25103139, 2014). "Together these data highlight the complex nature of MC4R signaling and how it affects not only obesity and metabolism, but also weight-loss." (PMID 24705671, 2014). "The first GWAS-derived loci detected were intronic variants in the FTO (fat mass and obesity-associated) gene and variants approximately 200 kb downstream of MC4R." (PMID 25154910, 2014). "A wealth of data exist that show association between carrying rare, presumably deleterious, MC4R variants and obesity." (PMID 24705671, 2014). "In summary, our data provides novel evidence that variation in the obesity associated gene MC4R is associated with improved quantitative ultrasound phenotypes, an important component of bone strength." (PMID 24516669, 2014). "Mutations that disrupt signaling through the melanocortin 4 receptor (MC4R) represent the commonest highly penetrant genetic form of obesity, being found in 2–5% of severely obese individuals." (PMID 25062455, 2014). "MC4R haploinsufficiency is associated with hyperphagia, binge eating, decreased energy expenditure and obesity." (PMID 25103139, 2014). "In the present study, we identified the association of obesity-related SNPs, rs12970134 near MC4R, rs10938397 near GNPDA2, and rs2260000 within BAT2, with the susceptibility of type 2 diabetes in a large Han Chinese population." (PMID 25093408, 2014).
Obesity (continued). "MC4R was initially identified as a gene predisposing to obesity and higher levels of BMI and fat mass." (PMID 25093408, 2014). "While carrying a rare MC4R allele is associated with obesity, carriers of rare variants exhibited comparable weight-loss after RYGB to non-carriers." (PMID 24705671, 2014). "Our longitudinal data with repeated BMI measures allowed a comprehensive assessment for the effect of MC4R on obesity risk over lifetime (age 5–50 years)." (PMID 25103139, 2014). "MC4R is crucial in the regulation of body weight and monogenic forms of obesity commonly result from mutations in its gene." (PMID 24516669, 2014). "While MC4R rare variants are highly associated with obesity, external factors contribute significantly to the obese phenotype." (PMID 24705671, 2014). "A limitation of the study is that biomarker data was not available in the PEAK-25 cohort, which would have enabled us to identify if there are age related effects associated with the homocysteine-MC4R-obesity relationship." (PMID 24516669, 2014). "One of the novel findings of our study is that MC4R is associated with altered vitamin D, folate and Hcy levels, which are associated with obesity." (PMID 24516669, 2014). "We and others have reported that mutations in MC4R are found in 5–6 % of patients with severe early-onset obesity and at a frequency of approximately 1/1,000 in the general UK population, making this one of the most common human genetic diseases." (PMID 25154910, 2014). "Common genetic variants 3′ of MC4R within two large linkage disequilibrium (LD) blocks spanning 288 kb have been associated with common and rare forms of obesity." (PMID 24820477, 2014). "Mutations in the MC4R are the most prevalent form of monogenic obesity identified to date accounting for up to 6% of patients with severe obesity." (PMID 23404466, 2013). "Our findings of sex-specific genetic effects on waist-hip-ratio as a measure of fat distribution are consistent with a study of families in whom MC4R mutations segregate that demonstrated larger effects on obesity in female compared to male mutation carriers." (PMID 23754948, 2013). "Recently, a study in Scotland reported that variants of common single nucleotide polymorphism around the melanocortin 4 receptor (MC4R) gene are associated with both obesity and colorectal cancer." (PMID 24073332, 2013). "Whilst obesity appears to be dominantly inherited, the penetrance of obesity with MC4R mutations is variable with mutations resulting in complete loss of function having a more severe phenotype." (PMID 23766565, 2013). "Haploinsufficiency, defined as loss of one copy of a gene via a mutation, of the melanocortin-4 receptor (MC4R) is the most common cause of monogenetic obesity in humans." (PMID 24159378, 2013). "The melanocortin-4 receptor (MC4R) is important for control of food intake, and loss of this receptor elicits obesity in laboratory animals." (PMID 24159378, 2013). "Two other obesity associated genes, MC4R and GNPDA2 were also identified by GWAS in Europeans and replicated in other studies." (PMID 23424664, 2013). "Mutations within MC4R lead to massive hyperphagia and severe, monogenic early onset obesity in humans." (PMID 24066140, 2013). "A genetic risk score constructed with the FTO, MC4R and six of the newly discovered loci performed poorly as a predictor of obesity and the explained variance of BMI was less than 1%." (PMID 24267414, 2013). "Genetic variants of the FTO gene rs9939609 A/T and the MC4R gene rs17782313 C/T have been associated with obesity." (PMID 23849767, 2013).
Obesity (continued). "The most common origin of monogenetic obesity in humans is deficiency, more specifically haploinsufficiency (where a single copy of a gene is inactivated by a mutation), of the MC4R." (PMID 24159378, 2013). "The observation that deletion of the MC4R results in a phenotype that is a virtual carbon copy of POMC-deficient mice (including late onset of obesity and diabetes) strongly supports this idea." (PMID 23543895, 2013). "The association of six European obesity-related SNPs in or near FTO, NPC1, ENPP1, NEGR1, GNPDA2 and MC4R genes with risk of obesity was tested in 1,463 school-aged Mexican children (Ncases = 514; Ncontrols = 949)." (PMID 23375129, 2013). "MC4R is a strong candidate gene for obesity because functional mutations of this gene are associated with monogenic forms of obesity." (PMID 24267414, 2013). "It should be pointed out that among over 150 missense variants in the MC4R gene there are polymorphisms predisposing to polygenic obesity, as well as mutations causing the monogenic type of obesity." (PMID 24142065, 2013). "The importance of the melanocortin peptides is confirmed by the demonstration of severe obesity associated with mutations of the melanocortin receptor (MC4R)." (PMID 23766565, 2013). "Mutations in MC4R are the most common single known cause of monogenic obesity, and variations in MC4R have been found in strong association with BMI in GWAS of individuals of European descent." (PMID 23577239, 2013). "The mice with functionally inactive MC4R had obesity strikingly reminiscent of the agouti syndrome, which indicates that the disturbances in MC4R signaling pathways were the primary cause of the agouti obesity." (PMID 24191197, 2013). "MC4R gene is also expressed in the hypothalamus, but when inactivated is associated with lower blood pressure, independently of obesity." (PMID 23849767, 2013). "In humans, haploinsufficiency, defined as the loss of one copy of a gene due to mutation, of the MC4R is the most common cause of monogenic obesity." (PMID 24159378, 2013). "In particular, common variants within the fat-mass and obesity associated (FTO) and melanocoritin 4 receptor (MC4R) genes are associated with modest effects on BMI (0.2–0.4 kg/m2 per allele) which translate into increased odds of obesity of 1.1–1.3 in adults." (PMID 23349760, 2013). "Over the past 15–20 years, mutations in a number of genes including leptin (LEP), leptin receptor (LEPR), pro-opiomelanocortin (POMC) and melanocortin-4 receptor (MC4R) have been associated with monogenic obesity." (PMID 23306188, 2013). "One of the most common forms of monogenic obesity, representing up to 5% of severe childhood obesity, is linked to melanocortin-4 receptor (MC4R) gene mutations." (PMID 22701495, 2012). "This is different than what was observed for another obesity-linked variant retained in the ER, MC4R I316S, which was rescued to the cell surface similarly by UBE-41 and by PBA exposure." (PMID 23251400, 2012). "Statistical and biological interactions with PA and diet modulate the effects of FTO and MC4R polymorphisms on obesity." (PMID 23284998, 2012). "The first cases of obesity due to MC4R mutations were reported in 1998, with the prevalence of mutations in this gene now estimated at 1/1000 and accounting for up to 6% of severe obesity cases." (PMID 23251400, 2012). "A disruption of melanocortin 4 receptor (MC4R) signalling, potentially in the paraventricular hypothalamic nucleus where Gnas is imprinted, was implicated as the likely cause for obesity and reduced energy expenditure." (PMID 22253771, 2012). "Although the Fat Mass and Obesity (FTO) and Melanocortin-4 Receptor (MC4R) genes have been consistently associated with obesity risk, the association between the obesity-risk alleles with type 2 diabetes is still controversial." (PMID 23130628, 2012).
Obesity (continued). "We have recently reported that obesity-linked MC4R variants are misfolded in the endoplasmic reticulum (ER) and targeted for degradation by ER-associated degradation (ERAD)." (PMID 23251400, 2012). "We performed a comprehensive meta-analysis of various studies from different ethnic populations to assess the association of the MC4R polymorphism with obesity risk." (PMID 23049848, 2012). "UBE1-41, a specific inhibitor of ubiquitin-activating enzyme 1, also improved cell surface expression of wt-MC4R and of the obesity-associated MC4R I316S variant." (PMID 23251400, 2012). "The present meta-analysis confirms the significant association of MC4R polymorphism with risk of obesity." (PMID 23049848, 2012). "In the same study, we found that the chemical chaperone PBA can increase folding and plasma membrane expression of wt-MC4R and of some obesity-linked MC4R variants including I316S, with increased signaling after stimulation with the agonist." (PMID 23251400, 2012). "We have recently reported that some obesity-linked MC4R variants are retained in the ER because they are misfolded." (PMID 23251400, 2012). "Mutations in the MC4R are the most common cause of monogenic childhood obesity and the severity of obesity can be quantitatively correlated to the impairment of signaling." (PMID 22479599, 2012). "The results indicate that heparanase inhibits obesity by degrading HS chains, presumably linked to syndecan-3, thereby suppressing the binding of AgRP to MC4R." (PMID 22479599, 2012). "As with obesity, the effect of the Ay allele on body length was considered to be mediated by the melanocortin 4 receptor." (PMID 23031221, 2012). "As far as we know this is the first time that a statistically significant interaction between the aggregate score of the FTO and the MC4R polymorphisms and physical activity on BMI and obesity is reported." (PMID 23284998, 2012). "Human genetic data and murine studies have implicated MC4R with energy balance regulation in the CNS, hence a potential target for treatment of obesity and eating disorders." (PMID 22479599, 2012). "UBE41 had much less profound effects on MC4R I316S, another obesity-linked MC4R variant trapped in the ER." (PMID 23251400, 2012). "Partial or total loss of MC4R function, as well as the variant rs17782313 mapped 188 kb downstream of MC4R, are positively associated with obesity." (PMID 23185251, 2012). "In another report it has been shown that resequencing MC4R resulted in the identification of low-frequency coding variants that explain approximately 2 to 3% of cases of severe obesity." (PMID 22474595, 2012). "Considering the significant gene-diet interaction results that we have obtained for the FTO and MC4R loci, it would be interesting in future studies to analyze this interaction for other polymorphisms previously associated with obesity and/or diabetes." (PMID 23130628, 2012). "Signaling via the type 4-melanocortin receptor (MC4R) is an important determinant of body weight in mice and humans, where loss of function mutations lead to significant obesity." (PMID 22848742, 2012). "Case #1: A white male had a novel c.815C>T (p.P272L) mutation in MC4R inherited from his mother who also had early-onset obesity." (PMID 23251400, 2012). "Carriers of obesity-linked MC4R variants present increased body mass index (BMI), hyperphagia, and hyperinsulinemia." (PMID 23251400, 2012). "Melanocortin-4 receptor (MC4R) mutations are the most frequent monogenic causes of severe early onset human obesity (up to 6%)." (PMID 23185251, 2012). "Then, we performed a meta-analysis to assess the association between rs17782313 polymorphism near the MC4R gene and obesity risk across different ethnic populations." (PMID 23049848, 2012). "Genome-wide association studies on Europeans have shown that two polymorphisms (rs17782313, rs12970134) near the melanocortin 4 receptor (MC4R) gene were associated with increased risk of obesity." (PMID 23049848, 2012).